RACGAP1 (Rac GTPase activating protein 1)
Diseases named in the same sentence as RACGAP1 in open-access papers (continued):
Sharing a sentence is not in itself a finding about the gene and the disease.
RACGAP1 also shares sentences with these, for which no sentence is quoted: meningioma (3 papers); pancreatic ductal adenocarcinoma (3); glioma (2); cholangiocarcinoma (1); Diabetic Nephropathy (1); endometriosis (1); liver disease (1); lung squamous cell carcinoma (1); multiple myeloma (1); nasopharyngeal carcinoma (1); neuroblastoma (1); non-small cell lung carcinoma (1); Obesity (1); rectal cancer (1); rheumatoid arthritis (1); sarcoma (1); skin cutaneous melanoma (1); stomach cancer (1); Ureteral obstruction (1); urothelial carcinoma (1); uterine cancer (1).